TIMP2 (TIMP metallopeptidase inhibitor 2)
Diseases named in the same sentence as TIMP2 in open-access papers (continued):
Sharing a sentence is not in itself a finding about the gene and the disease.
tumor (continued). "Given the in vivo anti-angiogenic activity of HSA/TIMP-2, we explored the regulatory effects of HSA/TIMP-2 on MMP-2, a key regulator of tumor angiogenesis known to be modulated through an interaction with TIMP-2." (PMID 22545131, 2012). "Taken together, these findings provide a useful basis for the in vivo mechanistic study of TIMP-2 anti-tumor activity and suggest that HSA/TIMP-2 holds promise as an anticancer drug." (PMID 22545131, 2012). "Nevertheless, the most relevant finding was the association between high CD68/(CD3+CD20) ratio and the expression of MMP-11 (stromalysin-3) or TIMP-2 by the MICs at the tumor center." (PMID 23300781, 2012). "This study is the first report of the in vivo mechanism underlying anti-tumor activity and anti-angiogenesis associated with MMP-2 modulation via TIMP-2 protein." (PMID 22545131, 2012). "Our data suggested a role for TIMP-2 in the prevention of tumor cell invasion because its expression is upregulated in CAPE-treated SCC-9 cells." (PMID 23320037, 2012). "Systemic administration of HSA/TIMP-2 effectively inhibited tumor growth at a minimum effective dose of 60 mg/kg." (PMID 22545131, 2012). "In conclusion, this study is the first to report that HSA/TIMP-2 has dose-dependent effects on tumor growth in male Balb/c nude mice, highlighting the importance of minimum effective dose determination on anti-tumor activity in vivo." (PMID 22545131, 2012). "In analyzing tumor vascularization by immunofluorescence staining for endothelial cell marker PECAM-1, the microvessels of HSA/TIMP-2-treated tumor tissue demonstrated a significant 39.2% decrease in PECAM-1 level compared with the control group (P<0.01)." (PMID 22545131, 2012). "In previous studies, TIMP-2 overexpression protected cancer cells from apoptosis and reduced cell invasion in various tumor cell lines." (PMID 23320037, 2012). "Our finding that high doses of HSA/TIMP-2 protein inhibit angiogenesis and subsequently inhibit tumor growth is consistent with the findings of previous TIMP-2 studies." (PMID 22545131, 2012). "Gene therapy studies using adenoviral and retroviral delivery systems in tumors have demonstrated a role for TIMP-2 in suppressing angiogenesis and subsequent tumor progression in animal models." (PMID 22545131, 2012). "A fusion protein formed from human TIMP-2 and human serum albumin was found to provide an improved pharmacokinetic profile and biodistribution in a tumor model and to provide an antiangiogenic effect." (PMID 23185522, 2012). "Collectively these studies indicate that perhaps effects of TIMP2 on tumor promotion or suppression are dependent on timing and the specific type of tumor." (PMID 22022379, 2011). "The TIMP2-armed CRAd delayed tumor growth and significantly increased survival when compared to the unarmed CRAd." (PMID 22022379, 2011). "TIMP-2 also significantly inhibited tumour cell invasion of Matrigel at 48 h, while inhibition by TIMP-1 was in significant." (PMID 21829200, 2011). "Among the TIMP family members, TIMP-2 is unique in its ability to inhibit tumor growth and angiogenesis through pathways also independent of MMP inhibition." (PMID 22022379, 2011). "In contrast, tumors from mice treated with Ad5/3-CXCR4-TIMP2 exhibited enhanced TIMP2 staining throughout the tumor, indicating that this oncolytic virus was effective in infecting and replicating throughout the entire tumor." (PMID 22022379, 2011). "In contrast, several animal studies utilizing viral delivery of TIMP2 have shown its utility to suppress tumor growth, migration and metastasis in various cancer models." (PMID 22022379, 2011). "Collectively, these data suggest that both viral replication and arming with TIMP2 contributed to delaying the onset of tumor growth." (PMID 22022379, 2011).
tumor (continued). "Four mammalian TIMPs have been identified thus far, among them TIMP2 has been most extensively studied due to its ability to inhibit tumor growth and angiogenesis by a variety of mechanisms independent of direct MMP-inhibition." (PMID 22022379, 2011). "Promoter hypermethylation and lost expression of TIMP-2 gene have been reported in prostate cells and tumor samples." (PMID 21152266, 2010). "TIMP-1 and TIMP-2 gene expression levels were significantly lower in tumors than in adjacent non-tumor tissue samples (p = 0.0169 and p = 0.0127, respectively)." (PMID 19144199, 2009). "Liposome-complexed TIMP2 DNA constructs administered to MMTVneu transgenic mice reduced tumor growth and effectively inhibited the occurrence of lung metastases." (PMID 18474097, 2008). "In tumour tissues, MMPs 2, 11, 14, 15 and TIMP-2 were expressed at a significantly higher level in stromal tissue when compared to tissue from the epithelially derived compartment (P<0.05)." (PMID 16465195, 2006). "MMP2 and TIMP2 were the major secretory proteins found in A549 tumour-conditioned medium, whereas MMP9 and TIMP1 were the key proteinases secreted by MDA-MB-231 cells." (PMID 16495926, 2006). "These genes are mainly characteristic of previously defined 'stromal' signature, but that are produced by both tumor and stromal cells including collagens, TIMP2, bFGF, vimentin and SPARC." (PMID 16042759, 2005). "The rate of detection of TIMP-2 in tumour cell cytoplasm increased with the depth of invasion (P = 0.03)." (PMID 10901373, 2000). "TIMP-2 mRNA and protein were present in all xenografts; interestingly, the strongest immunoreactivity of tumour cells was found at the border of necrotic areas." (PMID 10555745, 1999). "In situ hybridisation showed TIMP-1 and TIMP-2 transcripts predominantly over tumour stroma and gelatinases evenly distributed over both stromal and tumour cells." (PMID 1457364, 1992). "Notably, these effects were coupled with an increase in TIMP‐2, suggesting a shift toward a less invasive tumor phenotype." (PMID 41474368, 2026). "Furthermore, the ability of CUR to inhibit MMP-9 and upregulate the tissue inhibitor of metalloproteinases-2 (TIMP-2) significantly suppresses tumor angiogenesis, metastasis, and cell proliferation, thereby complementing the antitumor mechanisms of PTX." (PMID 40871063, 2025). "The expression of the putative miR-503 target genes strongly correlates with tumor growth, and, except for TIMP2, they have never been associated with MM." (PMID 39984959, 2025). "The current study is a continuation of our previous research, which focused on the role of other proteases such as metalloproteinases (MMP-9 and MMP-2) and their tissue inhibitors (TIMP-1 and TIMP-2) as candidates for tumor markers in gastro-intestinal malignancies, including CRC." (PMID 40725774, 2025). "Indeed, DNJ has been shown to inhibit the expression of MMP2 and MMP9, upregulate TIMP-2, and alter cell surface glycan-binding motifs, which are crucial in extracellular matrix remodeling, differentiation, and migration of tumor-derived cells." (PMID 40428492, 2025). "In addition, protein expression analysis of BTG1, CCNG1, EDG1, and TIMP2 in MM tissues in mouse tumor masses treated with LNPs-anti-miR-503 confirmed the q-PCR results and the opposite expression of miR-503 and of its target genes also in vivo." (PMID 39984959, 2025). "Another study found that Per1 knockout increased the expression of MMP9 and MMP2 and also reduced the expression of TIMP-2, which may lead to the observed increase in tumor cell invasion and migration." (PMID 38903177, 2024). "MMP3, TIMP1, and TIMP2 play critical roles in tumor invasion." (PMID 38921985, 2024). "However, MMP-2 indicated a limited value for tumor staging and prognosis in OC, suggesting better usefulness of TIMP-2 as a potential tumor marker, particularly when combined with SCC-Ag." (PMID 38673838, 2024).
tumor (continued). "We and others have illustrated how TIMP2 exhibits anti-tumor capabilities, and others have described how TIMP2 may protect against age-related neuronal dysfunction." (PMID 38313275, 2024). "TIMP2 belongs to the family of Tissue inhibitors of metalloproteinases, and there are conflicting reports on its role in cancer, which is closely related to the invasion and migration of tumor cells." (PMID 38982456, 2024). "To conclude, we present new evidence of the anti-tumor capabilities of TIMP2." (PMID 38234759, 2023). "There are accumulating data suggesting that HIF1α and HGF may act as pro-tumour factor while TIMP-2 is an anti-cancer regulator." (PMID 35953652, 2023). "Besides, the expression of 7 genes (EZH2, FLT1, IRS1, KDR2, MYB2, JUN, and TIMP2) was significantly different in metastatic tissue when compared with the primary tumor." (PMID 36879084, 2023). "Unlike propofol, sevoflurane exposure resulted in bigger tumour size, shorter survival time (assessed with the clinical endpoints, including body weight loss > 20% and tumour volume > 70 mm3), higher HGF, HIF1α, IL1β and TNFα expressions, and lower E-cadherin and TIMP-2 expressions." (PMID 35953652, 2023). "In the case of TIMP2, piperine regulated gene expression positively in CaSki cells and negatively in non-tumor cells (HaCaT); regarding protein expression, there was an increase in expression in CaSki and SiHa cells and a decrease in expression in HaCaT cells after treatment with piperine." (PMID 36678600, 2023). "mRNA expression of Mmp9, Egfr and Hmox1 (tumor progression), Timp1 and Timp2 (inhibitors of metalloproteinases) and Hif1α (hypoxia) evaluated in lung homogenates was significantly augmented in LLC-challenged Igf1rfl/fl mice, remaining unaltered in CreERT2 mice." (PMID 35688943, 2022). "Therefore, the function of TIMP2 is complex, and additional studies are needed to investigate the relationship between TIMP2 expression and tumor invasion." (PMID 36052250, 2022). "TIMP-2 is a 21 kDa protein with anti-apoptotic and pro-proliferative properties, while IGFBP7 is a 29 kDa protein which acts as an IGF-1 receptor antagonist that causes tumor suppression and regulates cellular aging by inhibiting kinase signaling." (PMID 36091391, 2022). "Some data suggests that TIMP2 biological activity acts as a tumor suppressor." (PMID 36624735, 2022). "Based on our study, further discovery of the systematic molecular mechanisms that how TIMP2 interacted with different signaling and other molecules or leads to different prognosis of cancer patients can pave the way for more effective tumor diagnosis and serve as a genetic treatment target." (PMID 36304987, 2022). "In contrast TIMP-2 is reported to suppress tumor growth and metastasis." (PMID 36551933, 2022). "TIMP2 was a kind of tissue inhibitor, which could inhibit tumor growth and invasiveness by restraining the activation of MMPs (matrix metalloproteinases)." (PMID 34798882, 2021). "Moreover, by Multivariate analysis using Cox’s proportional hazard model, high PD-L1 (p < 0.01), TWIST1 (p < 0.03), TIMP2 (p = 0.11) expression were independent and significant prognostic factors for tumor recurrence in NMIBC patients." (PMID 34885101, 2021). "Lastly, TIMP2, MMP2 and MMP14 are mediators of ECM degradation associated with tumor metastasis." (PMID 34140574, 2021). "The expression of TIMP-2 mRNA was quite pronounced in both the tumor and normal tissues." (PMID 34830452, 2021). "miR-149-3p could enhance proliferation and migration by targeting CDKN1A and TIMP2 in vitro, and promote tumor growth and weight in vivo." (PMID 34798882, 2021). "We were the first to discover the role of TIMP2 in inhibiting tumor invasion." (PMID 34638439, 2021). "The tumour microenvironment may provide paracrine cues that regulate these TIMP-2-dependent roles in cancer cells." (PMID 33023532, 2020). "Diffuse TIMP-2 staining was noted in the stroma of some tumours, which was mainly cytoplasmic." (PMID 33023532, 2020).
tumor (continued). "TIMP-2 diminishes cell proliferation, neoangiogenesis, and tumor growth." (PMID 33419373, 2020). "Furthermore, TIMP-2 concentrations in serum were inversely correlated with relative miR-130b expression in tumor tissues from the same patients with NSCLC." (PMID 31061410, 2019). "The balance between MMP2 and TIMP2 plays a key role in tumor cell invasion and metastasis." (PMID 31598171, 2019). "Present study is the continuation of our previous investigations, where we assessed whether the serum levels of MMP-2 and TIMP-2 might be used as potential tumor markers for gastric (GC), esophageal (EC) and colorectal cancer (CC)." (PMID 30719232, 2019). "Thence, it attracted our attention to investigate whether TIMP2 was a mediator for miR-93 tumor promotor role in OS cells." (PMID 31383784, 2019). "Our findings indicate that TIMP2 levels in the tumour microenvironment may have prognostic value in patients with PDAC." (PMID 31836008, 2019). "The combined analysis of MMP-2 and TIMP-2 with classical tumor markers (CA 19-9 and CEA) increased diagnostic sensitivity, however the highest value of this parameter was found for combined measurement of MMP-2 and TIMP-2 (96%)." (PMID 30719232, 2019). "Moreover, we showed that miR-130b expression levels in tumor tissues and TIMP-2 concentrations in serum from the same patients were inversely correlated." (PMID 31061410, 2019). "Finally, we examined the relationship between TIMP-2 concentrations in the serum and miR-130b expression in tumor tissues from patients with NSCLC." (PMID 31061410, 2019). "Moreover, the combined analysis of TIMP-2 with MMP-2 increased the diagnostic sensitivity up to 96%, and this value was higher than for the measurement of classical tumor markers in combination." (PMID 30719232, 2019). "The observed decrease in MMP-2 expression in tumor together with the increase of feature N simultaneously existed with the expression increase of MMP-2in the stroma and the expression decrease of TIMP-2 in the stroma, as well as the increase in the tumor (P=0.0085)." (PMID 31223594, 2019). "Importantly, an inverse correlation was observed between TIMP-2 concentrations in serum and miR-130b expression levels in tumor tissues of the same patients with NSCLC (r = −0.3081, p = 0.0248)." (PMID 31061410, 2019). "In conclusion, our study demonstrates that miR-93 may exert an oncogenic function while TIMP2 may act as a tumor suppressor on OS." (PMID 31383784, 2019). "In prolactinomas, TIMP-2 was found to be a marker for tumor invasion and recurrence." (PMID 32922863, 2018). "Few recent studies have shown the use of conditionally replicating adenoviruses (CRAd), which selectively kills tumor cells, loaded with TIMP-2 as a therapeutic transgene, targeting the matrix metalloproteinase in murine orthotopic model of disseminated ovarian cancer." (PMID 29393911, 2018). "The levels of both MMP-2 and TIMP-2 expressions in tumors may facilitate the initiation and progression of multiple biological behaviors required for tumor progression." (PMID 26729052, 2017). "Furthermore, the changes in RECK were more significant and pronounced relative to TIMP-2 indicating that it is a more reliable marker for tumour invasion." (PMID 28515436, 2017). "Other proteins present in these EVs are plasminogen activators, such as PA–PAI complexes, tissue type-PA (tPA) and urokinase type-PA (uPA), as well as MMP tissue inhibitors, such as TIMP1 and TIMP2, which contribute to the angiogenic activity related to tumor growth." (PMID 29261132, 2017). "Furthermore, we found that knockdown of DANCR increased the expression of TIMP2/3 in the metastatic foci of CW22Rv1-shDANCR compared with those of CW22Rv1-shNC, as detected by immunohistochemistry analysis of mouse metastatic tumor tissues." (PMID 27191265, 2016). "Notably, ITGB8, DICER1, INPP5A, PIK3R1, and TIMP2 are key tumor suppressors that were among up-regulated CRGs following CBX2 knockdown." (PMID 26877821, 2016).
tumor (continued). "The TIMP2, for tissue inhibitor of metalloproteinases 2, is known to antagonize the activity of matrix metalloproteinases and suppress tumor growth, angiogenesis, invasion, and metastasis; the mechanism of inhibition of this gene’s expression remains unknown." (PMID 26363785, 2015). "Thus, TIMP-2 interaction with MT1-MMP provides tumor cells with either pro- or anti-apoptotic signaling depending on the extracellular environment and apoptotic stimulus." (PMID 26331622, 2015). "Following this initial period, TIMP-2 expression and activity may, in turn, reduce tumor growth by inhibiting tumor angiogenesis and inducing tumor cell apoptosis." (PMID 26556867, 2015). "Among the TIMP family members, tissue inhibitor of metalloproteinase 2 (TIMP2) is a distinguished one, because it not only correlates with matrix remodeling and angiogenesis suppressing, but also participates in the process of tumor growth, inflammation and other diseases." (PMID 26314845, 2015). "Previously, it has been shown, in other tumors, that endothelial cells may respond to angiogenic factors, such as VEGF, by decreasing the synthesis of TIMP-2 to facilitate tumor angiogenesis and metastasis." (PMID 24527080, 2014). "Given the important roles of TIMP2 in tumor growth, angiogenesis, invasion and metastasis, it is rational to speculate that host genomic polymorphism of TIMP2 may influence the tumor occurrence." (PMID 25136829, 2014). "At the end of the experiment, the size or volume of the xenografts in NCTD or TIMP-2 group was decreased significantly in comparison with control group, with increased tumor inhibition (all P < 0.001), and tumor inhibitory rate in NCTD group were much less than that of TIMP-2 group (P < 0.01)." (PMID 24628713, 2014). "TIMP-2 is believed to suppress tumor invasion by inhibiting MMPs." (PMID 24591757, 2014). "In our study, an increase in the expression of both MMP-2 and TIMP-2 from normal oral epithelium to severe dysplasia suggested that the activation of MMP-2 is dependent on TIMP-2 acting as a cofactor, thereby providing a microenvironment that enhances the spread of tumor cells." (PMID 24591757, 2014). "Accordingly, the aim of this study was to determine, using a multivariable model, the independent prognostic value of several immunohistochemically detected tumour-associated molecules, such as MMP-9 and uPA in stromal cells and Ki-67, TIMP-2 and VEGF in cancer cells." (PMID 23289974, 2013). "Indeed, tumor cell migration and invasion were inhibited in vitro, whereas in vivo tumor growth inhibition was achieved through TIMP-2 mediated interaction with the tumor microenvironment, angiogenesis inhibition and induction of tumor cell apoptosis." (PMID 23371049, 2013). "Specifically, we show that the tumor suppressor gene E-cadherin is up-regulated by TIMP-2 overexpression in vitro and in vivo, contributing to the maintenance of cell-cell adhesion that may also contribute to inhibition of tumor growth." (PMID 23371049, 2013). "In addition, it is remarkable our finding indicating that if there is a high CD68/(CD3+CD20) ratio at the invasive front, most of MICs with a positive MMP-11 or TIMP-2 phenotype at the tumor center are macrophages." (PMID 23300781, 2012). "Also, tissue sections were stained with MMP-2, -9, -11, -14 and TIMP-2 antibodies, and immunoreactivity location, percentage of reactive area and intensity were determined at the invasive front and at the tumor center." (PMID 23300781, 2012). "In addition, it is interesting our finding indicating that if there is a high CD68/(CD3+CD20) ratio at the invasive front, most of MICs with a positive MMP-11 or TIMP-2 phenotype at the tumor center are macrophages (respectively)." (PMID 23300781, 2012). "TIMP-2 expression appears to have a tumor-promoting role in PCa." (PMID 22547956, 2011). "The TIMP2 gene was incorporated to inhibit tumor progression." (PMID 22022379, 2011).